SOD3 (superoxide dismutase 3)
Diseases named in the same sentence as SOD3 in open-access papers (continued):
Sharing a sentence is not in itself a finding about the gene and the disease.
atopic dermatitis (4 papers, 2020 to 2022). "In OVA-induced atopic dermatitis (AD)-like skin inflammation murine model, SOD3 production in MSCs synergistically enhanced their therapeutic potential." (PMID 32128111, 2020). "Our findings suggest that SOD3-MSCs can exhibit potent therapeutic efficacy against atopic dermatitis in vivo." (PMID 33238520, 2020). "SOD3-overexpressed MSCs (SOD3-MSCs) reduced the symptoms of murine model of atopic dermatitis (AD)-like inflammation, as well as the differentiation and activation of various immune cells involved in AD progression." (PMID 33238520, 2020). "Similarly, the treatment with SOD3 also found to suppress the serum IgE levels in house dust mite-induced atopic dermatitis-like skin inflammation." (PMID 35155837, 2022). "Similarly, in OVA-induced atopic dermatitis (AD)-like skin inflammation murine model, SOD3-transduced MSCs exhibited reduced H4R expression with suppressed ERK1/2, p38, JAK-STAT, and NF-κB activation." (PMID 32128111, 2020). "Superoxide dismutase 3 (SOD3) has been found to suppress IgE in various allergic diseases such as allergic conjunctivitis, ovalbumin-induced allergic asthma, and dust mite-induced atopic dermatitis-like skin inflammation." (PMID 35155837, 2022).
diabetic nephropathy (4 papers, 2014 to 2021). "The same group reported using SOD1- and SOD3-knockout diabetic mice to confirm the distinct role of SOD isoforms in diabetic nephropathy." (PMID 33477607, 2021). "Therefore, further experiments are needed to clarify the independent role of SOD3 in protecting against diabetic nephropathy." (PMID 33477607, 2021). "However, recent studies have reported that SOD3 has an independent role in protection against diabetic nephropathy." (PMID 33477607, 2021). "They suggested that SOD1 deficiency, but not SOD3 deficiency, increases renal O2•− and causes overt renal injury in C57BL/6-Akita diabetic mice and that SOD1 plays a more prominent role than SOD3 in the pathogenesis of diabetic nephropathy." (PMID 33477607, 2021).
fibrosis (4 papers, 2023 to 2025). the formation of excess fibrous connective tissue in an organ or tissue in a reparative or reactive process. "Thus, future studies should focus on SOD3 to show that the upregulation of SOD3 in neonatal RV is one of the underlying mechanisms that protects neonatal RV from fibrosis." (PMID 40394014, 2025). "For example, administering recombinant SOD3 to mice during the progression period of fibrosis improves lung architecture and function." (PMID 41502422, 2025). "Because CCDC80 and SOD3 were observed as the strongest SBCs for both fibrosis and NASH, we next investigated their effects on adipogenesis in vitro using an siRNA knockdown experiment." (PMID 37224770, 2023). "Furthermore, analogous studies have demonstrated that elevated SOD3 expression protects against tissue fibrosis characterized by excessive TGF-β1 activation, myofibroblast differentiation and collagen deposition." (PMID 37507914, 2023). "We observed significantly decreased differential expression of SOD3 in individuals with NAFLD, using 3 independent tests comparing individuals with steatosis, fibrosis, and NASH to those with healthy livers." (PMID 37224770, 2023).
Hepatic steatosis (4 papers, 2023 to 2025). Steatosis is a term used to denote lipid accumulation within hepatocytes. "Our findings identified SNPs significantly associated with disease risk, demonstrated altered expression of immune (IL-6, IL-8), antioxidant (SOD3, HMOX1), and lipogenic (ACACA, FASN) genes, and confirmed hepatic steatosis via ultrasonography." (PMID 41012815, 2025).
Hyperglycemia (4 papers, 2011 to 2025). An increased concentration of glucose in the blood. "Hyperglycemia-caused DM enhanced a significant reduction of the SOD3 in both DM1 (p = 0.004) and DM2 (p = 0.003) groups compared to the control group." (PMID 34326888, 2021). "Based on our data, attenuation of podocyte injury may be associated with reducing hyperglycemia, upregulation of SOD-1/SOD-3 mRNA expression, and downregulation of the TRPC6 mRNA expression in the CeA treatment in early hyperglycemia condition." (PMID 34326888, 2021). "Our findings emphasize a pronounced decrease in SOD3 in participants with T2DM, aligning with previous reports showing that impairments in antioxidant capacity are exacerbated by hyperglycemia." (PMID 40362367, 2025). "The phenomenon of persistent hyperglycemia may induce oxidative stress by damaging the vascular endothelium and decreasing the binding of SOD3 to the vascular wall due to nonenzymatic glycation of SOD3." (PMID 35740095, 2022). "Our findings reveal a stronger negative correlation between miR-21 and SOD3 in T2DM, underscoring how “inflammaging,” hyperglycemia, and miR-21–SOD3 dysregulation jointly escalate OxS." (PMID 40362367, 2025). "However, during the hyperglycemia, the SOD is unable to eliminate the excess ROS, which results in suppression of the antioxidant enzymes such as SOD1, SOD3, and catalase but not SOD2." (PMID 34326888, 2021).
liver fibrosis (4 papers, 2013 to 2025). "SOD3 is downregulated in liver fibrosis, and its deficiency promotes hepatic stellate cell activation and epithelial–mesenchymal transition (EMT), thereby aggravating liver injury and collagen deposition." (PMID 41153430, 2025). "SOD3 is also implicated in other disease states where its deficiency induces activation of hepatic stellate cells, thereby increasing deposition of collagen in liver fibrosis, and its overexpression attenuates neural injury resulting from ischemic stroke." (PMID 41502422, 2025). "Notably, their findings suggest that SOD3 deficiency exacerbated liver fibrosis by suppressing AMPK signaling." (PMID 38136160, 2023). "The impact of acetylation on SOD3 found herein may likewise be of critical importance in liver fibrosis." (PMID 41502422, 2025). "Moreover, very little is known about the regulation and potential of SOD3 in the prevention of CCl4-induced liver fibrosis." (PMID 23341968, 2013).
viral infection (4 papers, 2016 to 2023). "In comparison with the WT group cells, the SOD3 overexpression group cells showed dramatically reduced MDA levels in A549 cells, indicating that SOD3 overexpression can counteract the oxidative stress caused by viral infection." (PMID 36829913, 2023). "In addition, overexpression of SOD3 greatly reduced the levels of ROS caused by influenza A virus infection, regulated the inflammatory response to virus infection by inhibiting the phosphorylation of p65 of the NF-κB signaling pathway, and inhibited virus-induced apoptosis to a certain extent." (PMID 36829913, 2023). "Further study may define the mechanism of SOD3 induction in I-Mac and delineate insight of a role of SOD3 in virus infection in macrophages." (PMID 28240310, 2017). "SOD1, SOD3, catalase, and Nrf2 were downregulated by viral infection." (PMID 26761025, 2016).
breast tumors (3 papers, 2014 to 2025). "The expression of the tumor suppressor gene superoxide dismutase 3 (SOD3) and glutathione S-transferase Mu 2 (GSTM2) has been implicated in aggressive, high-grade breast tumors, where promoter hypermethylation is associated with poor survival in patients." (PMID 39908270, 2025). "The protective effect of SOD3 against oxidative DNA damage was demonstrated in 17β-estradiol- (E2-) induced breast tumors in female rats and in MCF-10 breast epithelial cells that significantly express SOD3 after treatment with the antioxidant butylated hydroxyanisole (BHA) or vitamin C." (PMID 34725562, 2021). "We show that Sod3 is at least in part responsible for the ability of VEGF-C to protect against ROS-induced cell death and to mediate breast tumor progression." (PMID 25358638, 2014).
cerebral infarction (3 papers, 2019 to 2024). An ischemic condition of the brain, producing a persistent focal neurological deficit in the area of distribution of the cerebral arteries. "LIF protects neurons by reducing oxidative stress during cerebral infarction by upregulating SOD3 expression." (PMID 36792628, 2023).
Cerebral ischemia (3 papers, 2014 to 2019). Restriction of arterial blood supply to the brain associated with insufficient oxygenation to support the metabolic requirements of the tissue. "This study aimed to investigate the effect of SOD3 overexpression on cerebral ischemia‐reperfusion injury in rats." (PMID 31461803, 2019). "Our results indicated that MSCs transfected with SOD3 can effectively alleviate cerebral ischemia‐reperfusion injury in rats." (PMID 31461803, 2019). "It has been shown that Sod3 is important for the integrity of many tissues, such as lung, kidney pancreas and heart, and is protective in brain ischemia reperfusion in mouse." (PMID 29523072, 2018). "Increased oxidative damage, despite the presence of higher levels of SOD3, was described in a model of cerebral ischemia." (PMID 26266917, 2014).
coronary atherosclerosis (3 papers, 2019 to 2025). Atherosclerosis of the coronary vasculature. "Recently gene therapy studies have indicated that SOD3 has a good effect on some diseases caused by superoxide free radical, Hattan, Chilian, Park, and Rocic (2007) found that SOD3 intervention can alleviate the symptom damage in coronary atherosclerosis." (PMID 31461803, 2019). "Gene polymorphisms: SOD2 rs4880, SOD3 rs2536512 and rs2855262, GPX rs3828599, and GSTT1 (deletion) were evaluated the associations with HTG, low HDL-C, high TG/HDL-C ratio, and severity of coronary atherosclerosis." (PMID 31396447, 2019). "Gene polymorphisms in superoxide dismutase (SOD2 and SOD3), glutathione peroxidase-3 (GPX3), and glutathione S-transferase theta-1 (GSTT1) may enable oxidative stress-related lipid abnormalities and severity of coronary atherosclerosis." (PMID 31396447, 2019).
dermatitis (3 papers, 2013 to 2021). An inflammatory process affecting the skin. "The immune-modulatory and anti-inflammatory effects of MSCs that overexpress SOD3 also proceed via the inhibition of histamine H4 receptor expression and consequently, of the associated signaling cascade in murine dermatitis-like skin inflammation, as induced by ovalbumin." (PMID 33805942, 2021). "In the present study, we demonstrated that transduction of SOD3 in hUCB-MSCs improved the immunoregulatory and therapeutic functions of cells and their EVs against in vitro immune cell activation and in vivo dermatitis manifestation, respectively." (PMID 33238520, 2020). "We found that both SOD3-MSCs and their EVs can reduce the symptoms of the murine dermatitis model by attenuating inflammation and fibrosis." (PMID 33238520, 2020). "Taken together, our findings suggest that SOD3 overexpression in MSCs results in the improved immunomodulatory abilities of T-cell immunity, as well as the amelioration of in vivo symptoms observed in the murine dermatitis model." (PMID 33238520, 2020). "Similarly, SOD3 inhibited TLR2/MAPKs/NF-κB and the NLRP3 inflammasome, and consequently suppressed inflammation in a mouse model of Propionibacterium acnes-induced skin inflammation." (PMID 33805942, 2021).
dyslipidemia (3 papers, 2019 to 2025). "We further demonstrated that high GRS derived from combined SOD2, SOD3, GPX3, and GSTT1 polymorphisms have a strong association with such atherogenic dyslipidemia." (PMID 31396447, 2019). "OS in conditions like dyslipidemia often triggers cellular antioxidant responses, including the induction of protective buffer molecules and enzymes such as copper zinc superoxide dismutases (SOD1 and SOD3)." (PMID 39997704, 2025).
endometritis (3 papers, 2024 to 2025). An acute or chronic, usually bacterial infectious process affecting the endometrium. "Buffaloes with endometritis showed significantly decreased levels of expression of the NDUFS5, RXFP1, TGF-β, CAT, SOD3, and GPX transcription factors." (PMID 40266925, 2025). "In the buffaloes affected by endometritis, the expression levels of the RXFP1, NDUFS5, TGF-β, SOD3, CAT, and GPX genes were significantly reduced." (PMID 39195794, 2024). "The RXFP1, NDUFS5, TGF-β, SOD3, CAT, and GPX genes were expressed at substantially lower levels in endometritis-affected buffaloes." (PMID 38459095, 2024). "The levels of the PRLR, LTF, CLA-DRB3.2, beta defensin, TLR2, TLR4, and CCL5 genes were significantly up-regulated in postparturient goats with endometritis compared to tolerant ones, while the GPX4, GST, SOD3, CAT, and ATOX1 gene patterns demonstrated the opposite tendency." (PMID 39195794, 2024).
idiopathic pulmonary arterial hypertension (3 papers, 2019 to 2023). A sporadic form of pulmonary arterial hypertension (PAH) characterized by elevated pulmonary arterial resistance leading to right heart failure. "HDAC3 inhibition can significantly promote SOD3 expression which is beneficial to the alleviation of idiopathic pulmonary arterial hypertension (IPAH)." (PMID 37072432, 2023). "Inhibition of HDAC3 significantly promoted SOD3 expression and benefited the alleviation of idiopathic pulmonary arterial hypertension (IPAH)." (PMID 37759978, 2023). "The expression/activity of SOD3 in the lung from human idiopathic pulmonary arterial hypertension was reduced, and this downregulation could be reversed by the treatment of PASMCs with class I HDAC inhibitors or HDAC3 siRNA, suggesting that histone deacetylation negatively regulates SOD3 expression." (PMID 30881600, 2019).
infarction (3 papers, 2012 to 2020). A localised pathological necrosis of tissue resulting from obstruction of the blood supply usually by a thrombus, an embolus, or vascular torsion. "Taken together, these results demonstrate that SOD3-tranduced skeletal muscle-derived cells may have potential for use in the regenerative treatment of the post-infarction heart." (PMID 32887483, 2020). "Therefore, enhanced SOD3 gene activity may promote better human SkMDS/PCs proregenerative properties when promptly delivered to the post-infarction site." (PMID 32887483, 2020).
inflammatory bowel disease (3 papers, 2021 to 2025). A spectrum of small and large bowel inflammatory diseases of unknown etiology. "However, the effect of SOD3 and the underlying mechanism in inflammatory bowel disease (IBD) have not been uncovered." (PMID 34208517, 2021).
lung adenocarcinoma (3 papers, 2021 to 2025). A carcinoma that arises from the lung and is characterized by the presence of malignant glandular epithelial cells. "There are significant differences in SOD3 expression in lung squamous carcinoma and lung adenocarcinoma tissues and normal tissues." (PMID 35356201, 2022). "In lung adenocarcinoma, SOD3 expression was significantly different in patients with different stages, but no obvious pattern was observed." (PMID 35356201, 2022). "We also analyzed the difference of SOD3 expression between lung adenocarcinoma and lung squamous cell carcinoma." (PMID 35356201, 2022).
parasite infection (3 papers, 2022 to 2024). "SOD3-deficient mice had a substantially longer survival time and lower parasitemia than control mice after infection, whereas SOD3-overexpressing mice were much more vulnerable to parasite infection." (PMID 38851821, 2024). "Overall, our findings expose active fronts in the arms race between the parasites and host immune system and provide insights into the roles of SOD3 in shaping host innate immune responses to parasite infection." (PMID 38851821, 2024). "In the E8.5 infection group, E16.5 placental Sod3 transcripts tended to correlate negatively with both peripheral parasitemia at sacrifice and parasitemia AUC." (PMID 35312688, 2022). "E8.5 infected mice had elevated transcripts for Ifnγ, Tnf, Il10, Cox1, Cox2, Sod1, Sod2, Cat, and Nrf2, while Sod3 was the only transcript that correlated with parasitemia." (PMID 35312688, 2022). "SOD3, which belongs to part of the superoxide dismutase (SOD) protein family, is another gene of interest involved in responses to mixed parasite infection." (PMID 39342330, 2024).
prostatitis (3 papers, 2020 to 2021). An infectious or non-infectious inflammatory process affecting the prostate gland. "An experiment recently found that the Zn-binding proteins superoxide dismutase 3 (SOD3) and carbonic anhydrase 1 (CA1) were present in high quantities in prostatitis when compared to control." (PMID 34070833, 2021).
rheumatoid arthritis (3 papers, 2019 to 2022). A chronic, systemic autoimmune disorder characterized by inflammation in the synovial membranes and articular surfaces. "This association has previously been observed in patients presenting active rheumatoid arthritis, establishing that the level of sICAM in serum correlates negatively with the level of SOD3." (PMID 31326693, 2019). "Several studies have focused on the possible role of SOD3 in rheumatoid arthritis." (PMID 31015473, 2019). "Therefore, SOD3 plays an important part in rheumatoid arthritis." (PMID 31015473, 2019).
vasculitis (3 papers, 2020 to 2022). "Moreover, endogenous MSCs were also found to release significant higher amounts of SOD3 in immune complex-induced vasculitis in contrast to healthy controls, thus indicating that MSCs abrogated the oxidative stress-induced tissue damage through the secretion of SOD3." (PMID 32128111, 2020). "In the same murine vasculitis model, intra-dermal injection of AT-MSCs significantly reduced the numbers of neutrophil elastase- and myeloperoxidase-positive neutrophils, NET formation, and vascular leakage via upregulation of SOD3." (PMID 36613507, 2022). "Interestingly, in a mouse model of vasculitis, MSCs inhibit NET production and uncontrolled respiratory bursts by overactivated neutrophils and effectively reduce the release of oxygen radicals from neutrophils by secreting the antioxidant enzyme superoxide dismutase 3 (SOD3)." (PMID 35154331, 2022).
vitiligo (3 papers, 2013 to 2022). Generalized well circumscribed patches of leukoderma that are generally distributed over symmetric body locations and is due to autoimmune destruction of melanocytes. "Recently, we have shown that SOD2 and SOD3 polymorphisms may be genetic risk factors for susceptibility and progression of vitiligo and contribute to increased transcript levels and activity of SOD2 and SOD3 in patients." (PMID 24312346, 2013).
acute pancreatitis (2 papers, 2020 to 2022). An acute inflammatory process that leads to necrosis of the pancreatic parenchyma. "This study aimed to evaluate changes in IL-6 concentration and the concentration/activity of superoxide dismutase isoenzymes (SOD1, SOD2, and SOD3) in the blood of patients with acute pancreatitis (AP) in terms of rs1800795 polymorphism in the IL6 gene." (PMID 35205334, 2022). "This study was aimed at evaluating the impact of acute pancreatitis on the changes in concentration and activity of all three superoxide dismutase isoenzymes: cytosolic SOD1, mitochondrial SOD2 and extracellular SOD3 in extracellular (plasma) and intracellular (erythrocyte lysate) compartments." (PMID 33019780, 2020).
allergic conjunctivitis (2 papers, 2022 to 2023). "In experimental allergic conjunctivitis and ovalbumin-induced allergic asthma murine models, treatment with SOD3 showed reduced serum level of OVA-induced IgE." (PMID 35155837, 2022). "Previous studies showed that treatment with SOD3 showed reduced serum level of OVA-induced IgE in experimental allergic conjunctivitis and ovalbumin-induced allergic asthma murine models." (PMID 35155837, 2022).